IL17C (interleukin 17C)
Diseases named in the same sentence as IL17C in open-access papers (continued):
Sharing a sentence is not in itself a finding about the gene and the disease.
colitis (12 papers, 2015 to 2025). Inflammation of the colon. "Surprisingly, Tgfb1, Il17ra, Il23a, Il6ra, Ror1, Tnf, Tgfbr2, Ccr2, and Il17c were downregulated by cigarette smoke exposure in TNBS-induced colitis Gpr15−/− mice compared with similarly treated Gpr15+/+ mice." (PMID 40957881, 2025). "Gpr15 deficiency significantly weakened the association between Il17c and immune cells, particularly Th17 cells, in the TNBS-induced colitis group following cigarette smoke exposure." (PMID 40957881, 2025). "Past studies have revealed that when compared with wild-type mice, the DSS-induced mice colitis model showed significantly increased levels of IL-17C, and DSS-treated IL-17C knockout mice exhibit exacerbated intestinal inflammation." (PMID 37554552, 2023). "In a dextran sulfate sodium (DSS)-induced colitis mouse model for IBD, IL-17C exhibits a protective role in colitis development." (PMID 34122457, 2021). "Another group examined the role of IL-17RE in this model confirming those findings of the IL-17C/RE axis assuming a crucial role in protection against bacteria-driven DSS-induced colitis." (PMID 32174926, 2020). "A recent study showed that IL-17C expression increased in human CRC samples and murine tissues of colitis-associated colon cancer, facilitating the development of CRC." (PMID 32492770, 2020). "Others have previously demonstrated the direct and protective role of IL-17C in regulating occludin production by colonic epithelial cells in mice during acute experimental colitis." (PMID 31221216, 2019). "The length of the colon in Il17c−/− mice was significantly shortened compared with wild-type mice on Day 8 during DSS-induced colitis." (PMID 30356086, 2018). "Although IL17RE has been reported to be a functional receptor for IL17C as well as mediating the mucosal immunity in the small intestine of mice during acute experimental colitis, the overall function of IL17REL still remains unclear." (PMID 28886140, 2017). "In a model of acute colitis, I17c−/− mice challenged with dextran sulfate sodium (DSS) had a significantly worse outcome than mice with physiological IL-17C production, which is reflected by earlier and more pronounced weight loss and colonic shortening." (PMID 32174926, 2020). "Along these lines, IL-17C-/- mice are partially protected from experimental autoimmune encephalomyelitis (EAE), the mouse model of multiple sclerosis and DSS colitis." (PMID 25849644, 2015). "Our data suggest that IL17re/IL17C expression may be elevated in response to long-term Blastocystis ST3 colonization and induced in the response to colitis." (PMID 33897648, 2021). "On the other hand, IL-17C is important for development of T cell-independent DSS-induced colitis and LPS-induced endotoxin shock, but not for bleomycin-induced pulmonary fibrosis, papain-induced airway eosinophilia or LPS-induced airway neutrophilia." (PMID 30356086, 2018). "Mice lacking IL-17C exhibited exacerbated DSS-induced colitis and IL-17C was shown to induce the production of occludin, participating in the establishment of intestinal barrier functions." (PMID 30127781, 2018).
lung carcinoma (10 papers, 2018 to 2025). "IL-17C plays a crucial role in facilitating the infiltration of tumor-associated neutrophils and promoting the proliferation of lung cancer cells." (PMID 38255960, 2024). "We have shown before that sub-chronic and chronic NTHi-induced inflammation promotes the recruitment of neutrophils in lung cancer models in an IL-17C-dependend manner." (PMID 33411748, 2021). "Here, we used a Kras-driven lung cancer model to examine the function of IL-17C in inflammation-promoted tumor growth." (PMID 31316109, 2019). "This suggests that IL-17C has a specific role in the promotion of lung cancer only in the presence of exogenous lung inflammation or insult, such as bacterial colonization in COPD patients." (PMID 31316109, 2019). "We detected IL-17C in human lung cancer samples and showed that IL-17C mediates the recruitment of neutrophils and lung tumor growth in a metastatic lung cancer model of acute lung inflammation." (PMID 31316109, 2019). "We therefore examined the function of IL-17C in inflammation-promoted tumor growth in a Kras-driven lung cancer model." (PMID 31316109, 2019). "Additional studies are needed to determine whether targeted inhibition of innate cytokines, such as IL-17C or IL-6, with therapeutic antibodies enhance the response to PD-1 blockade in lung cancer." (PMID 31316109, 2019). "Our results suggest that strategies targeting innate immune mechanisms, such as blocking of IL-17C, may improve the response to anti-PD-1 treatment in lung cancer patients." (PMID 31316109, 2019). "In IL-17C-deficient mice, nontypeable Haemophilus influenza induced less neutrophil lung infiltrates and promoted less tumorigenesis, thus linking IL-17C to bacteria and lung cancer." (PMID 33244315, 2020). "IL-17C, which promotes neutrophilic inflammation, was also found abundant in human lung cancer samples, and IL-17C is a negative prognostic factor in patients with lymph node metastasis." (PMID 33244315, 2020). "Because blocking IL-17C signaling significantly reduces the number and extension of colonic tumors in mice, MOR106 might be investigated in human colorectal and lung cancer." (PMID 33244315, 2020). "In addition, lung cancer studies used IL-17C knockout (KO) mouse models, rather than direct in vitro proliferation and migration assays, eliminating confounding factors and providing insight into the direct role of IL-17C." (PMID 40974979, 2025).
atherosclerosis (7 papers, 2017 to 2023). A disease characterized by the build-up of fatty material and calcium deposition in the arterial wall resulting in partial or complete occlusion of the arterial lumen. "Least absolute shrinkage and selection operator, random forest, support vector machine- recursive feature elimination show that IL17C and ACOXL were identified as diagnostic markers of atherosclerosis." (PMID 37173646, 2023). "In this study, multiple machine learning methods (LASSO, RF, SVM-RFE) identified IL17C (AUC = 0.92) and ACOXL (AUC = 0.90) as novel diagnostic biomarkers for atherosclerosis, and verified in other datasets." (PMID 37173646, 2023). "IL17C and ACOXL were diagnostic genes of atherosclerosis and associated with higher incidence of ischemic events." (PMID 37173646, 2023). "In conclusion, we identified IL17C and ACOXL were diagnostic genes of atherosclerosis and associated with higher incidence of ischemic events." (PMID 37173646, 2023). "In addition to IL-17A and IL-17F, IL-17C and IL-17E can also aggravate psoriatic lesions; meanwhile, IL-17A and IL-17C can enhance atherosclerotic plaque instability, and IL-17E is protective against atherosclerosis." (PMID 35514987, 2022). "However, the subclinical atherosclerosis-associated plasmatic signature in the HIVneg population was different and marked with the upregulation of TNF-α and IL-27 and downregulation of CCL26 and IL-17C (p=0.02, 0.043, 0.011 and 0.021, respectively)." (PMID 33936102, 2021). "Interestingly, IL-17C appears to also have a role in pathogenesis of atherosclerosis." (PMID 33244315, 2020). "IL-17C and TNF-β, elevated in AD, have overlapping signaling pathways with IL-17A/F and TNF-α, which are thought to contribute to atherosclerosis in psoriasis." (PMID 28821884, 2017). "Moreover, it has been reported that smooth muscle cell derived IL-17C could recruit TH17 cells to perivascular and promotes atherosclerosis." (PMID 36187757, 2022).
autoimmune disease (7 papers, 2017 to 2024). A disorder resulting from loss of function or tissue destruction of an organ or multiple organs, arising from humoral or cellular immune responses of the individual to their own tissue constituents. "As excessive TH17 cell activity is linked to many autoimmune diseases, IL-17C-mediated stimulation of the TH17 cell represents a cause for TH17 autoimmunity upstream of main effector cytokines like IL-17A and F." (PMID 32174926, 2020). "Many studies report that IL17C expression is upregulated at an early stage in both infectious and autoimmune diseases." (PMID 32174926, 2020). "It has been shown that IL-17RE is highly expressed in Th17 cells and that the IL-17C/IL-17RE-axis enhances the expression of cytokine by effector Th17 cells in a in a model of autoimmune disease." (PMID 32641167, 2020). "Recently, IL-17RE has been characterized as the functional receptor for IL-17C, and IL-17C plays a critical role in the regulation of host defense against infections and autoimmune disorders." (PMID 30534126, 2018). "It has been widely reported in the literature that many cytokine and chemokine genes (e.g., TNF-a, IL-8, CXCL2, CXCL3, CXCL10, LIF, IL-17C and IL-23A) are the basis of autoimmune disorder pathways that are characterized by inflammation." (PMID 28099447, 2017). "Neutralizing IL-17C is an intriguing approach in the treatment of autoimmune diseases as it might hamper TH17 function in general and not only the impact signaling of the signature cytokine IL-17A." (PMID 32174926, 2020). "As IL-17C has been reported promote the production of IL-17A by Th17 lymphocytes in inflammatory conditions (such as autoimmune disease), the authors concluded that these effects may be due more to the promotion of IL-17A than to IL-17C alone." (PMID 31507598, 2019). "The second pro-inflammatory cytokine, IL17C, a member of the IL17 family, plays an essential role in immunopathology, autoimmune diseases, and cancer progression." (PMID 37228491, 2023).
colorectal cancer (6 papers, 2019 to 2022). A primary or metastatic malignant neoplasm that affects the colon or rectum. "Moreover, the angiogenic activity of IL-17C was found to be highly associated with colorectal cancer cell malignancy in vitro and increased tumorigenesis in vivo." (PMID 32492770, 2020). "In the present study, IL-17C can promote angiogenesis and migration in malignant colorectal cancer cell, DLD-1, suggesting that IL-17C contributes to the steps of tumorigenesis in chronic tumor environment." (PMID 32492770, 2020). "IL-17C is an interesting target in colorectal cancer because IL-17C has been found upregulated in these tumors, and in mice IL-17C was modulated by the gut microbiota." (PMID 33244315, 2020). "In our clinical trial, circulating inflammatory cytokines of TNF-α, IL-10, IL-12, IL-17A, IL-17C and IL-22 remained high in colorectal cancer patients even after removal of tumor." (PMID 31340751, 2019). "Interleukin-17C (IL-17C) was identified to promote colorectal cancer (CRC) progression." (PMID 32492770, 2020). "In order to address whether IL-17C confers tumor-promoting activities in the in vivo model of colorectal cancer, DLD-1 cells were subcutaneously inoculated into the flanks of nude mice (n = 10 per group) and IL-17C (1 μg/tumor) was injected peritumorally for 10 days." (PMID 32492770, 2020).
COVID-19 (6 papers, 2022 to 2025). A disease caused by infection with severe acute respiratory syndrome coronavirus 2. "Further research to clarify the mechanisms underlying the downregulation of IL-17C during symptomatic COVID-19 will have important implications in our understanding of COVID-19 pathogenesis, which is critical for clinical management and identification of new possible targets for treatment." (PMID 35479098, 2022). "Two proteins, namely IL17C and NT3 exhibited significantly increased levels among recovered COVID-19 patients." (PMID 40475767, 2025). "CCL23, among the other seven proteins (IL-17C, MMP-10, FGF-19, FGF-21, FGF-23, and CXCL5), was higher in asymptomatic COVID-19 patients than in patients with symptoms." (PMID 37834869, 2023). "Among the 12 patients who did not generate detectable antibodies, we observed a significantly elevated level of IL17C and a protein in the PPAR signaling pathway, namely, FABP6, compared to patients with COVID-19 with detectable antibodies." (PMID 37047248, 2023). "On the contrary, IL17C and NT3 levels increased significantly among recovered COVID-19 patients." (PMID 40475767, 2025). "Related to this, serum levels of IL-17C were found to be lower in participants with gastrointestinal (GI) symptoms than in those with no GI symptoms in hospitalized COVID-19 patients." (PMID 35479098, 2022). "Importantly, IL-17C, MMP-10, FGF-23 and CCL23 are upregulated only in asymptomatic participants early after infection, which strongly suggests their role in the control of COVID-19 clinical signs." (PMID 35479098, 2022).
fungal infections (6 papers, 2015 to 2024). "Another IL-17 family member, IL-17C, is a critical factor that potentiates inflammatory responses and causes host injury during fungal infection, and further investigation is needed to explore its role during influenza virus infection." (PMID 28912779, 2017). "Increased epithelial expression of IL-17C has been observed in response to a variety of bacterial, viral, and fungal infections, but the role of IL-17C appears variable, as both protective and pathogenic functions have been reported in various bacterial or fungal infections." (PMID 32232015, 2020). "Further studies that specifically investigate the role of IL-17C on mold infections are warranted to pinpoint its pathophysiologic role during invasive fungal infections." (PMID 38407673, 2024). "On the other hand, IL-17C induces lethal inflammation by exacerbating secretion of proinflammatory cytokines, contributing to the development of systemic fungal infection." (PMID 32849528, 2020). "IL-17C is a member of the IL-17 cytokine family produced by epithelial cells, and is induced in response to bacterial, viral, or fungal infections." (PMID 32232015, 2020). "Interestingly, high IL-17C expression has been noted in kidney epithelial cells following fungal infection, whereas lack of IL-17C in mice was associated with lower renal damage and improved survival." (PMID 32849528, 2020). "Similarly, there may be a role for IL-17C/IL-17RE signaling in other types of fungal infections." (PMID 25849644, 2015). "The IL‐17 family of cytokines consists of six groups: IL‐17A, IL‐17B, IL‐17C, IL‐17D, IL‐17E and IL17‐F, which are involved in the development of autoimmunity, inflammation, tumours, host defences against bacterial and fungal infections, and mucosal host defence mechanisms." (PMID 38363001, 2024).
inflammatory bowel disease (6 papers, 2018 to 2025). A spectrum of small and large bowel inflammatory diseases of unknown etiology. "Furthermore, TNF-α treatment increased the expression of genes encoding various proinflammatory cytokines such as IL-6, IL-8, IL-1β, and IL-17C, involved in the progression of inflammatory bowel disease." (PMID 34208517, 2021). "Further diseases involving the IL-17C/RE axis include psoriasiform skin lesions in inflammatory bowel disease (IBD) patients under anti-TNF-α treatment, recurrent aphthous ulcers, LPS-induced endotoxin shock, and different forms of cancer." (PMID 32174926, 2020).
periodontitis (6 papers, 2016 to 2025). An acute or chronic inflammatory process that affects the tissues that surround and support the teeth. "In patients with aggressive periodontitis, reduced levels of DNA methylation in the promoters of CCL25 and IL17C compared to healthy controls have been identified." (PMID 33256844, 2020). "A decrease in methylation level was found in promoter regions of IL17C and CCL25 in periodontitis patients indicating an increase in gene expression." (PMID 29201597, 2017).
dermatitis (5 papers, 2023 to 2024). An inflammatory process affecting the skin. "While the role of IL-17C in skin inflammation remains unclear, overexpression of IL-17C in KCs promotes psoriasiform skin inflammation in a murine model, and IL-17C–deficient mice are protected from imiquimod-elicited inflammation." (PMID 38470486, 2024). "This loop is further amplified by IL-17C–TCF4 autocrine regulation of ZC3H12A and IL-17C regulation of NFKBIZ to promote self-sustaining skin inflammation." (PMID 38470486, 2024). "TCF4 expression negatively corresponds to skin inflammation in an IL-17C–IL-17RA/RE–dependent manner." (PMID 38470486, 2024). "IL-17C can trigger more complex immune responses, as shown in a transgenic mouse model of dermatitis where Il17c expression was directed to the epidermis." (PMID 38470486, 2024). "ZC3H12A/Regnase-1 has been previously shown to suppress imiquimod-elicited skin inflammation by regulating IL-17A and IL-17C responses." (PMID 38470486, 2024). "The elimination of IL-17C on its own also eliminated skin inflammation supporting prior work showing that antibody treatment with anti–IL-17C improves inflammation in acute models of Ps and AD." (PMID 38470486, 2024). "This demonstrated that Tcf4 negatively regulated Il17c and Zc3h12a in vivo to promote skin inflammation." (PMID 38470486, 2024). "Moreover, interference with cutaneous TCF4 using topical application of Tcf4 siRNA worsens skin inflammation by increasing cutaneous Il17c and Zc3h12a and by increasing skin infiltrating CD3+ T cell numbers, resulting in worsened acanthosis." (PMID 38470486, 2024). "Using ELISA, we examined IL-17C protein expression in several Ps animal models of psoriasiform-like dermatitis, including the KC-Tie2 mouse model, the topical imiquimod treated C57BL/6 mice, the Klk6+ model, and a model in which Il17c is genetically overexpressed in KCs." (PMID 38470486, 2024). "The increases in TCF4 in these mice further validate the capacity for skin inflammation to regulate TCF4 expression, with KC data suggesting that TNF-α, IL-17A, and IL-17C likely contribute to regulating (decreasing) TCF4." (PMID 38470486, 2024). "A negative TCF4/IL-17C/ TNF-a/ IL-17A feedback loop decreases TCF4 in an IL-17RA/RE-dependent manner and is further amplified by IL-17C/TCF4 regulation of ZC3H12A and IL-17C regulation of NFKBIZ, resulting in self-sustaining skin inflammation." (PMID 38470486, 2024). "Oral propionate and the HFD reduced mRNA expression of IL-17A, IL-17C, IL-17F, IL-22, IL-1β, IL-6, TNF-α, CXCL1, CXCL2, and CCL20 in imiquimod-induced dermatitis." (PMID 37762500, 2023). "Oral propionate decreased mRNA expression of IL-17A, IL-17C, IL-17F, IL-22, IL-6, IL-1β, TNF-α, CXCL1, and CCL20 in imiquimod-induced dermatitis in comparison between NDIS versus NDIP." (PMID 37762500, 2023). "MEG3 is co-expressed with anti-inflammatory genes that are downregulated by IL17C and IL17RB, and it is negatively correlated with genes that when knocked out in mice, it induces chronic inflammation and dermatitis." (PMID 36869839, 2023). "Oral propionate reduced inflammatory infiltrates and epidermal Ki67+ cells and reduced mRNA levels of IL-17A, IL-17F, IL-17C, IL-22, IL-1β, IL-6, TNF-α, CXCL1, CCL20 and increased those of TGF-β1and IL-10 in imiquimod-indued dermatitis." (PMID 37762500, 2023). "All mice with oxazolone-induced dermatitis had a dramatic increase in IL-1β, IL-4, IL-6, IL-10, TNF-α, IFN-γ, IL-16, IL-17C, IL-17E, IL-17F, IL-21, IL-22, and MIP-3a, whereas the concentrations of IL-12p70, IL-2, IL-17A, and IL-23 were lower in dermatitis mice." (PMID 37889696, 2023). "In imiquimod-induced dermatitis, IL-17A, IL-17F, and IL-22 may be mostly derived from Th17 cells or γδT17 cells, while CXCL1, CXCL2, CCL20, and IL-17C may be mainly produced by epidermal keratinocytes." (PMID 37762500, 2023).
dermatitis (continued). "Finally, Zc3h12a expression correlated with measures of skin inflammation, such that Zc3h12a increased in KC-Tie2 mice compared with control animals and decreased in the absence of Il17c, Il17re, and Il17ra." (PMID 38470486, 2024).